RNU6-957P (RNA, U6 small nuclear 957, pseudogene)
Gene: Small nuclear RNA gene on chromosome 6 (110,722,250 to 110,722,348, reverse strand). Ensembl gene ENSG00000200522.
Homologues: Orthologues: chimpanzee U6 (96% identical), macaque U6 (95% identical), mouse Gm26176 (85% identical), dog U6 (84% identical), tropical clawed frog U6 (82% identical). Paralogues in human: RNU6-1152P (91% identical), RNU6-97P (91% identical), RNU6-16P (90% identical), RNU6-820P (90% identical), RNU6-11P (89% identical), RNU6-19P (89% identical), RNU6-211P (89% identical), RNU6-35P (89% identical), RNU6-37P (89% identical), RNU6-434P (89% identical), RNU6-509P (89% identical), RNU6-851P (89% identical), and 1287 more.